KIF18A (kinesin family member 18A)
Description:
Microtubule-depolymerizing kinesin which plays a role in chromosome congression by reducing the amplitude of preanaphase oscillations and slowing poleward movement during anaphase, thus suppressing chromosome movements. May stabilize the CENPE-BUB1B complex at the kinetochores during early mitosis and maintains CENPE levels at kinetochores during chromosome congression.
Synonyms: MS-KIF18A; DKFZP434G2226; PPP1R99
Tractability: Small molecule: a structure with a bound ligand is known; a high-quality ligand is known. PROTAC: UniProt records ubiquitination sites on it; ubiquitination databases record sites on it; a small molecule that binds it is known.
Target class: Other cytosolic protein
Gene: Protein-coding gene on chromosome 11 (28,020,618 to 28,108,183, reverse strand). Ensembl gene ENSG00000121621.
Subcellular location: Cell projection, ruffle; Cytoplasm; Nucleus; Cytoplasm, cytoskeleton, microtubule organizing center, centrosome
Subcellular location (Human Protein Atlas): Cytokinetic bridge; Microtubules
Pathways (Reactome):
Cell Cycle: Amplification of signal from unattached kinetochores via a MAD2 inhibitory signal; EML4 and NUDC in mitotic spindle formation; Mitotic Prometaphase; Resolution of Sister Chromatid Cohesion; Separation of Sister Chromatids
Hemostasis: Kinesins
Immune System: MHC class II antigen presentation
Signal Transduction: RHO GTPases Activate Formins
Vesicle-mediated transport: COPI-dependent Golgi-to-ER retrograde traffic
Gene Ontology:
Molecular function: actin binding; microtubule binding; microtubule plus-end binding; plus-end-directed microtubule motor activity; protein binding; tubulin-dependent ATPase activity; ATP binding; cytoskeletal motor activity; microtubule motor activity
Biological process: microtubule depolymerization; mitotic metaphase chromosome alignment; mitotic sister chromatid segregation; cellular response to estradiol stimulus; microtubule-based movement; mitotic cell cycle
Cellular component: caveola; cytoplasm; intercellular bridge; kinetochore microtubule; microtubule cytoskeleton; nucleus; ruffle; cytosol; kinesin complex; mitotic spindle astral microtubule; mitotic spindle midzone; centrosome; kinetochore; spindle microtubule
Genetic constraint (gnomAD): Loss-of-function variants: 24 observed, 46.35 expected, observed/expected ratio (o/e) 0.52, 90% interval 0.37 to 0.73. The upper end of that interval is the gene's LOEUF score, 0.73, which puts it in group 2 of 6, group 1 being the genes least tolerant of losing a copy. Missense variants: 565 observed, 611.52 expected, observed/expected ratio (o/e) 0.92, 90% interval 0.86 to 0.99. Synonymous variants: 225 observed, 211.32 expected, observed/expected ratio (o/e) 1.06, 90% interval 0.95 to 1.19.
Homologues: Orthologues: chimpanzee KIF18A (99% identical), macaque KIF18A (97% identical), dog KIF18A (86% identical), pig KIF18A (85% identical), rabbit KIF18A (85% identical), guinea pig KIF18A (79% identical), mouse Kif18a (76% identical), rat Kif18a (75% identical), tropical clawed frog kif18a (57% identical). Paralogues in human: KIF18B (35% identical), KIF13B (25% identical), KIF1A (25% identical), KIF1B (25% identical), KIF13A (24% identical), KIF19 (23% identical), KIF17 (23% identical), KIF3B (23% identical), KIF16B (22% identical), KIF21B (22% identical), KIF3C (22% identical), KIF21A (22% identical), and 29 more.
Diseases named in the same sentence as KIF18A in open-access papers:
KIF18A is named in the same sentence as 59 diseases in open-access papers, as found by Europe PMC text mining. Sharing a sentence is not in itself a finding about the gene and the disease. The quoted sentences say what the papers report.
breast carcinoma (20 papers, 2015 to 2025). "Zhang reported that overexpression of KIF18A is associated with breast cancer metastasis and a short life span." (PMID 35464837, 2022). "KIF18A overexpression in human breast cancer has been closely associated with tumor grade, metastasis, and poor survival." (PMID 31392101, 2019). "It was also reported that high KIF18A expression is significantly associated with the progression of breast cancer, renal cell carcinoma, and colon cancer." (PMID 30872592, 2019). "KIF18A is also associated with metastasis of solid tumors (e.g., breast cancer)." (PMID 37346073, 2023). "KIF18A has also been associated with metastasis in solid tumours (e.g. breast cancer)." (PMID 30662724, 2018). "In breast cancer, KIF18A overexpression is correlated with tumor grade, metastasis and poor survival, while ablation of KIF18A dramatically restrains proliferation of breast cancer cells in vitro and in vivo via inhibiting PI3K/Akt pathway." (PMID 40175357, 2025). "Overexpression of KIF18A and aberrant expression of β-catenin are considered proto-oncogenes of breast cancer development." (PMID 38195458, 2024). "There was a highly significant relationship between the intensity of KIF18A and β-catenin expression in the breast carcinoma group, as most of the cases that showed strong KIF18A expression also showed strong β-catenin (p<0.001)." (PMID 38195458, 2024). "In a previous study, KIF18A has been identified as a potential therapeutic target for human breast cancer." (PMID 37182175, 2023). "Compared with normal tissue, the transcription abundance of KIF18A was promoted in most of the solid tumour tissues, including breast cancer, bladder cancer, colorectal cancer etc.." (PMID 37708299, 2023). "Another kinesin, KIF18A, facilitates the proliferation of colorectal and breast cancer cells through the regulation of centrosome fragment formation." (PMID 35803737, 2022). "High expression of KIF18A has been confirmed in multiple cancers such as breast cancer, lung cancer, and colorectal cancer." (PMID 35677036, 2022). "Silencing of KIF10 and KIF18A were both reported inhibitions to the proliferation of breast cancer cells via deregulating cell division." (PMID 32322170, 2020). "Elevated expression levels of kinesins KIF14, KIF4A, KIF20A, and KIF23, KIF2C, and KIFC1 have been reported in breast cancer cell lines, other kinesins KIF10, KIF18A, and KIF15 have been linked to prognostic indicators in breast cancer patients." (PMID 32346924, 2020). "Of the key genes unique to basal-like breast cancer, the expression levels of only CDC7, KIF18A, STIL, and CKS2 were associated with patient survival time (P < 0.05)." (PMID 33066779, 2020). "Some researchers even advocate measurement of KIF18A levels in patients with estrogen receptor positive (ER+) breast cancer (BC) prior to receiving endocrine therapy." (PMID 31392101, 2019). "Kif18A expression in breast cancers correlates with tumor grade, metastasis and survival, whilst suppression of Kif18A expression in breast cancer cells inhibits tumor growth in vivo." (PMID 28218637, 2017). "For example, Kif18A is overexpressed in human breast cancer at both mRNA and protein levels, and the degree of Kif18A expression is associated with tumor grades, metastasis and survival." (PMID 25884224, 2015). "KIF18A and β-catenin could be poor prognostic markers and predictors of aggressive behavior of breast cancer." (PMID 38195458, 2024). "Taken together, KIF18A expression in breast cancer could be used to tailor treatment options for breast cancer patients." (PMID 38195458, 2024). "KIF18A expression is low in normal tissues and high in solid tumors, including breast cancer (BRCA), hepatocellular carcinoma (HCC) and lung adenocarcinoma (LUAD), colorectal cancer(COAD), renal cell carcinoma (RCC), and head and neck squamous cell carcinoma (HNSCC)." (PMID 36830695, 2023).
breast carcinoma (continued). "Kif18a, kinesin family number 18a, which has function to produce force and movement along microtubules, was previously found to be deregulated in different cancers including breast cancer." (PMID 30961553, 2019). "Kif18A is overexpressed in human colorectal and human breast cancers." (PMID 28218637, 2017). "Furthermore, the reduction of KIF18A significantly induced apoptosis in human breast cancer cells." (PMID 35464837, 2022). "Thus, KIF18A testing of patients with ER-positive breast cancer prior to treatment could guide clinicians’ decision-making on whether the patients would benefit from endocrine therapy." (PMID 33066779, 2020). "Knocking down of KIF2C, KIF3C, KIF22, KIF18A and KIF24 inhibited proliferation of breast cancer cells via different mechanisms including G2/M phase arrest, delayed exit from mitosis, deregulating cell division and restoring ciliation." (PMID 32322170, 2020). "In breast cancer, few previous studies investigated the significance of KIF18A expression, which are not enough to establish its potential role in breast cancer." (PMID 38195458, 2024). "The relationship between KIF18A and β-catenin in breast cancer was not previously investigated." (PMID 38195458, 2024). "However, to the best of our knowledge, the relationship between KIF18A and β-catenin in breast cancer was not previously investigated." (PMID 38195458, 2024). "High KIF18A H score values were associated with poor prognostic factors such as high grade, advanced stage, nodal metastasis, distant metastasis, high grade of associated DCIS, poor NPI, presence of lympho-vascular invasion, PR negative, high Ki67 status, and Her2neu-enriched breast cancer." (PMID 38195458, 2024).
hepatocellular carcinoma (13 papers, 2014 to 2025). A malignant tumor that arises from hepatocytes. "We also detected the expression of signal pathway-related proteins in hepatoma cells after KIF18A knockdown with the aim of exploring the association between KIF18A and related signalling pathways." (PMID 29466986, 2018). "Several studies have shown that Kif18a is a novel biomarker for breast and colorectal cancer, and Kif18a overexpression is also associated with unfavorable prognosis in primary hepatocellular carcinoma." (PMID 30459823, 2018). "In this study, we explored the potential molecular mechanisms underlying the biological behavioural changes of hepatoma cells after KIF18A dysregulation to find new diagnostic targets or potential therapeutic targets for HCC." (PMID 29466986, 2018). "For example, KIF18A is involved in several forms of cancer, including colorectal, breast and hepatocellular cancer." (PMID 32253833, 2020). "In previous several studies, KIF18A was known to be associated with signalling pathways including Akt and metastasis‐related proteins (MMP‐7 and MMP‐9) in hepatoma cells and involved in Akt signalling pathways during human breast carcinogenesis." (PMID 32253833, 2020). "To further explore the changes in the tumour formation ability of hepatoma cells after KIF18A gene knockdown, we used HepG2 cells that were stably transfected with shRNA-KIF18A subcutaneously injected in nude mice." (PMID 29466986, 2018). "KIF18A-silenced hepatoma cells were subcutaneously injected into nude mice to verify the tumorigenicity of KIF18A." (PMID 29466986, 2018). "KIF18A is associated with a variety of tumours; however, the specific mechanism of action of KIF18A in hepatocellular carcinoma (HCC) remains unclear." (PMID 29466986, 2018). "We detected the expression of KIF18A in tumour and adjacent tissues as well as cell proliferation, cell invasion and migration in hepatoma cells after silencing KIF18A." (PMID 29466986, 2018). "The expression of cell cycle-related protein (cyclin B1), invasion and metastasis-related proteins (MMP-7 and MMP-9) and Akt-related proteins in hepatoma cells was also decreased after knocking down KIF18A." (PMID 29466986, 2018). "To further explore the effect of KIF18A on the biological behaviour of hepatoma cells, we knocked down the KIF18A gene in two hepatoma cell lines to investigate the changes in their biological activity." (PMID 29466986, 2018). "Based on the results above, we constructed a possible signal pathway of KIF18A that affects cell proliferation, cell invasion and migration of hepatoma cells." (PMID 29466986, 2018). "KIF18A also promotes invasion and metastasis of hepatoma cells via MMP-7/MMP-9-related pathway." (PMID 30813560, 2019). "Another study demonstrated that KIF18A is involved in the proliferation and motility of hepatocellular carcinoma (HCC) cells by regulating the cell cycle and signaling pathways linked to MMP-7/9." (PMID 35464837, 2022). "In hepatoma cells, silencing KIF18A reduced the expression of cyclin B1, MMP-9, MMP-7, and Akt-related proteins and inhibited hepatoma cell growth, invasion, and metastasis." (PMID 37965453, 2023). "We have selected several genes (SPP1, FLT3, KIF18A, SOCS2) of unclear significance in hepatocellular carcinoma." (PMID 37346073, 2023). "HPA analysis of protein expression showed that PRDX6, GCLM, HTATIP2, NOL10, KIF18A, RAP2A and GDI2 were highly expressed in the hepatocellular carcinoma tissues compared with normal control tissues." (PMID 34760691, 2021). "By knocking down the expression of KIF18A in hepatoma cells, we detected biological behavioural changes of HCC cells and explored the correlation between KIF18A and some signalling pathway-related proteins (Akt, Aurora A, cyclin B1, MMP-7, etc.)." (PMID 29466986, 2018).
hepatocellular carcinoma (continued). "This study aims to explore the role of KIF18A in the epithelial-mesenchymal transition (EMT) of liver cancer cells through the 5-LOX-dependent arachidonic acid pathway, and to construct a prognostic model to predict the prognostic risk of patients with hepatocellular carcinoma (HCC)." (PMID 41082523, 2025).
glioma (11 papers, 2015 to 2025). A benign or malignant brain and spinal cord tumor that arises from glial cells (astrocytes, oligodendrocytes, ependymal cells). "The findings displayed that KIF18A was positively linked with cell cycle, proliferation, and invasion of glioma." (PMID 36830695, 2023). "In Multivariate Cox regression analysis, the elevated expression of KIF18A was found to be an independent risk factor for poor prognosis in glioma patients." (PMID 35591854, 2022). "KIF18A was highly expressed in glioma tissues, and KIF18A expression was associated with age, World Health Organization grade, isocitrate dehydrogenase (IDH) status, 1p/19q codeletion, primary therapy outcome, and overall survival (OS)." (PMID 35591854, 2022). "We found that compared with normal tissues, KIF18A was highly expressed in glioma, and elevated expression of KIF18A was markedly associated with poor prognosis in patients with glioma." (PMID 35591854, 2022). "Studies have also found that high expression of KIF18A may indicate an increased risk of malignant transformation from low-grade gliomas to high-grade gliomas." (PMID 37759912, 2023). "However, in this study, we further investigated whether KIF18A is an independent risk factor affecting the prognosis of glioma, and explored the relationship between KIF18A expression and immune cells infiltration." (PMID 35591854, 2022). "The analysis indicated an inverse relationship between the methylation level of KIF18A and glioma grade." (PMID 40110038, 2025). "For example, high KIF18A expression is correlated increased infiltration of cytotoxic T cells, dendritic cells, NK cells, T helper cells, Th2 cells, and macrophages in glioma samples." (PMID 40175357, 2025). "TTBK2, NAV1, and CTTNBP2 were considered as protective factors, while SRCIN1, TRIO, KIF18A, and SLAIN2 were risk factors for glioma." (PMID 36979179, 2023). "Further in vitro experiments on glioma cell lines (U87 and U251) confirmed that KIF18A’s specific inhibitor BTB-1 inhibited the proliferation of glioma cells significantly, and the cell cycle stagnated in G2/M phase." (PMID 35677036, 2022). "In this study, we performed an in-depth and all-inclusive bioinformatics analysis of KIF18A expression in gliomas according to some clinical datasets, and its role as a potential therapeutic target and independent prognostic factor was evaluated." (PMID 35591854, 2022). "The time-dependent ROC curve showed that the expression level of KIF18A had a good predictive effect on glioma survival." (PMID 35591854, 2022). "The results suggested that patients with higher grade of glioma tend to have more KIF18A expression." (PMID 35591854, 2022). "This is the first investigation into the expression of KIF18A and its prognostic value, potential biological functions, and effects on the immune system and mitosis in glioma patients." (PMID 35591854, 2022). "To further clarify the role of KIF18A in glioma, we analyzed the mRNA expression of KIF18A in different clinical subgroups." (PMID 35591854, 2022). "Meanwhile, our study has suggested that in the KIF18A high expression group, macrophages were significantly recruited into the glioma immune microenvironment." (PMID 35591854, 2022). "Taken together, glioma displays prominently higher KIF18A expression than that in normal brain tissue at both the mRNA and protein levels." (PMID 35591854, 2022). "Moreover, TTBK2, NAV1, and CTTNBP2 were protective factors for glioma, while SRCIN1, TRIO, KIF18A, and SLAIN2 were risk factors." (PMID 36979179, 2023). "KIF18A upregulation contributes to the malignant progression and unfavorable prognosis of various types of cancer, including breast, hepatocellular, clear cell renal, prostate, esophageal carcinomas, and lung adenocarcinoma, especially glioma." (PMID 36979179, 2023). "In summary, KIF18A mRNA expression is related to the clinical characteristics of glioma, and its high expression might suggest a poor prognosis." (PMID 35591854, 2022).
glioma (continued). "In conclusion, our results suggest that KIF18A may be useful as a new prognostic indicator for gliomas." (PMID 35591854, 2022). "The increased expression of KIF18A in glioma was verified in clinical samples and U87 cell line." (PMID 35591854, 2022). "Therefore, to evaluate its potential therapeutic value, we treated glioma cells with BTB-1, a specific small-molecule inhibitor of KIF18A, to evaluate its effect on glioma cell function." (PMID 35677036, 2022). "In conclusion, our results suggested that KIF18A might affect the prognostic of glioma patients through its involvement in mitosis and regulation in immune cell infiltration." (PMID 35591854, 2022). "Therefore, the mechanism of treating glioma with KIF18A as a target is worthy of further study." (PMID 35677036, 2022). "Finally, immune filtration analysis suggested that KIF18A might be able to regulate the immune microenvironment of gliomas." (PMID 35591854, 2022). "Therefore, we assume that KIF18A is a candidate gene of glioma." (PMID 35464837, 2022). "KIF18A might be a new biomarker and therapeutic target for glioma patients." (PMID 35591854, 2022). "In summary, KIF18A may be a potential biomarker and a promising therapeutic target for gliomas." (PMID 35591854, 2022). "With further analysis, KIF18A may serve as an independent prognostic indicator for human glioma." (PMID 35591854, 2022). "In addition, some studies have found that KIF18A expression may be related to the prognosis of patients with glioma." (PMID 35591854, 2022). "Compared with the normal samples, except for SLAIN2, the CTTNBP2, KIF18A, NAV1, and TRIO protein expression in glioma was elevated, while SRCIN1 and TTBK2 were decreased." (PMID 36979179, 2023). "Our study found that compared with normal tissues, CTTNBP2, KIF18A, NAV1, SLAIN2, and TRIO were upregulated in glioma, while SRCIN1 and TTBK2 were downregulated." (PMID 36979179, 2023). "In glioma cells, PPP1CA collaborates with KIF18A to regulate cancer cell proliferation." (PMID 39664902, 2024). "Moreover, analysis of genes and proteins that interact with KIF18A showed that several molecules related to cell cycle and cell division, such as RRP7A, ANAPC4, WEE1, CDC20, and NDC80, were enriched in glioma." (PMID 35591854, 2022). "In addition, the expression of KIF18A in GBM, LGGs and all gliomas was significantly higher than that in normal brain tissue." (PMID 35591854, 2022). "However, the correlation and clinicopathological significance of KIF18A expression in glioma have not been studied, and further research is needed." (PMID 35591854, 2022).